BDNF (brain derived neurotrophic factor)
Diseases named in the same sentence as BDNF in open-access papers (continued):
Sharing a sentence is not in itself a finding about the gene and the disease.
neurodegenerative disease (continued). "Not only is BDNF increasingly considered a neurotrophin, it is also seen as an immunotrophin, epitheliotrophin and metabotrophin, which would explain why, besides psychiatric and neurodegenerative diseases, somatic illnesses have also been related to BDNF." (PMID 21247257, 2012). "If the BDNF reduction in these neurodegenerative diseases involves a mechanism common to that of diabetic retinopathy, lutein administration might also be considered as a therapeutic strategy for these neuronal diseases." (PMID 22211688, 2012). "Treated with appropriate dose of BDNF may significantly improve the effect of EGF-dependent NSPCs to control neurodegenerative diseases or injury." (PMID 22146375, 2011). "In light of our findings, it is attractive to speculate that differential regulation of nine BDNF exon mRNAs would become apparent in different neurodegenerative diseases in which BDNF levels are altered." (PMID 17149751, 2007). "Moreover, BDNF has neuroprotective properties, which may be of great importance in the context of neurodegenerative diseases or neural injuries, because many factors may stimulate BDNF expression." (PMID 40722844, 2025). "Our review presents the first integrated framework linking BDNF/proBDNF signaling with downstream apoptotic regulation and their regulatory mechanisms, like receptor dynamics and proteolytic and transcriptional regulation, across multiple neurodegenerative diseases, including AD, PD, and HD." (PMID 40430064, 2025). "The corroboration of mechanistic pathways and personalizing exercise-induced BDNF will provide an exercise-mediated intervention to bridge the gap for the prolonging cognitive health and wellbeing and addressing the rising burdens of neurodegenerative diseases." (PMID 40362507, 2025). "Therefore, dysregulated communication between BDNF and mitochondria may severely disrupt cellular energy metabolism and contribute to the pathogenesis of neurological disorders, especially neurodegenerative diseases." (PMID 39656488, 2024). "Conversely, reduced BDNF levels or impaired BDNF signaling may lead to decreased GLUT-1 expression and glucose transport, compromising neuronal energy metabolism and increasing susceptibility to age-related cognitive decline and neurodegenerative diseases." (PMID 39656488, 2024). "Therefore, BDNF serum level is functionally altered in different neurodegenerative diseases." (PMID 38006577, 2024). "At the same time, BDNF and its high-affinity Tyrosine Kinase receptor B (TrkB) play an important role in supporting the survival of various neuron population in central nervous system disease (CNS), which help to protect neurons from neurodegenerative diseases, including AD." (PMID 37221495, 2023). "An increasing number of studies have attested that BDNF is relevant to the occurrence, development and treatment of neurodegenerative diseases, and it is one of the most studied neurotrophic factors in the field of neurobiology in relation to neurodegenerative diseases." (PMID 37450039, 2023). "In addition, since decreased levels of BDNF have been observed in several neurodegenerative diseases, and ZIKV is potentially associated with the development and/or progression of neurodegenerative diseases, it would be interesting to study the role of BDNF repression in this context." (PMID 37515107, 2023). "Decreased BDNF levels may precede or follow the onset of neurodegenerative diseases." (PMID 37009109, 2023). "Therefore, it is highly possible that the ARMS regulates BDNF secretion by modulating Syt4 levels, and may thus play a key role in the regulation of nociception and neurodegenerative diseases." (PMID 38069318, 2023). "Thus, changing the BDNF through different interventions could positively affect the brain’s neuronal health and cognition, and prevent neurodegenerative diseases." (PMID 36671818, 2023).
neurodegenerative disease (continued). "By artificially enhancing BDNF levels and stimulating neurogenesis, researchers may unlock new possibilities for therapeutic interventions aimed at improving cognitive function in cancer survivors or patients suffering from neurodegenerative disease." (PMID 37507961, 2023). "Moreover, BDNF-TrkB activity is altered in several neurodegenerative diseases, including ALS, and this may suggest a correlation with neuronal damage." (PMID 35625004, 2022). "BDNF system activation has been shown to enhance a healthy aging process, and the administration of exogenous BDNF may be able to regenerate neurons in certain neurodegenerative diseases." (PMID 35625880, 2022). "Regular exercise likely protects from neurodegenerative disease both by an upregulation of antioxidative stress defences and related beneficial mitochondrial adaptations as well as indirectly by the regulation of neuroprotective factors, such as brain-derived neurotrophic factor (BDNF) via ROS." (PMID 34204228, 2021). "Therefore, it is not surprising that BDNF is implicated in several neurodegenerative diseases, including Alzheimer’s (AD), Parkinson’s (PD), Huntington’s (HD) diseases and other neuropsychiatric disorders." (PMID 34833132, 2021). "However, regardless of their definite positive effects, therapeutic applications of natural neurotrophins like NGF and BDNF, for treatment of neurodegenerative diseases, are limited due to their inability to cross blood brain barrier and also susceptibility to degradation by peripheral peptidases." (PMID 32390854, 2020). "The key idea of this work is to use a low dose BDNF solution to avoid the possible side effects of current therapies (such as sensitization and allergic reactions), supporting with experimental data a new potential therapeutic approach to treat or prevent neurodegenerative diseases." (PMID 32397504, 2020). "However, in recent years, the neuroprotective effects of estrogen have been widely discussed, and similar to brain-derived neuroprotective factor (BDNF) which is synthesized by the brain tissue, estrogen ameliorates several neurodegenerative diseases to maintain cerebral homeostasis." (PMID 33390881, 2020). "Therefore, the activation of the TrkB/Akt/Nrf2/ARE pathway, accompanied by stabilization of the TrkB/CREB/BDNF autocrine loop, may be important for the prevention and treatment of neurodegenerative diseases." (PMID 31861353, 2019). "Hence, considering the role of BDNF/TrkB during development and pathological situations such as in neurodegenerative diseases, TrkB transactivation offers alternative methods to modulate BDNF/TrkB, opening new therapeutic avenues for the treatment of neurodegenerative disorders." (PMID 31456666, 2019). "In some instances, poorer neurocognition could be attributed to neurodegenerative diseases itself rather than BDNF polymorphism, confounding the actual extent of effect from the BDNF genotype." (PMID 29858545, 2018). "The concept that BDNF-based synaptic repair may carry therapeutic potential in neurodegenerative diseases is beyond the scope of the present discussion and detailed reviews regarding synaptic dysfunction in neurodegenerative diseases can be seen in several previous publications." (PMID 28273832, 2017). "Thus BDNF-based therapies have been proposed for Alzheimer's and other neurodegenerative disease." (PMID 28424591, 2017). "Therefore, Müller glial BDNF-TrkB signalling is not only involved in neuroprotection, but also in neurogenesis, indicating that TrkB in glia may be a good therapeutic target for neurodegenerative diseases." (PMID 27657046, 2016). "Thus, the promotion of endogenous BDNF upregulation may be key to neurodegenerative disease treatment." (PMID 26667114, 2015).
neurodegenerative disease (continued). "In addition to the increased pro-inflammatory mediators in the brain in neurodegenerative diseases, neurotrophic factors, such as brain-derived neurotrophic factor (BDNF), glial cell-derived neurotrophic factor (GDNF) and insulin-like growth factor (IGF)-1, are impaired in these diseases." (PMID 26729090, 2015). "Despite the cross-sectional character of the studies reviewed, the hypothesis may be put forward that a post-menopausal drop in oestrogen levels results in reduced BDNF levels, explaining the increased vulnerability of middle-aged and older women to neurodegenerative disease." (PMID 21247257, 2012). "Emerging evidence suggests that inosine enhances brain-derived neurotrophic factor (BDNF) signaling, which plays a vital role in neuronal survival, synaptic plasticity, and cognitive function in neurodegenerative diseases." (PMID 41169479, 2025). "THR activation enhances the expression of brain-derived neurotrophic factor (BDNF) through MAPK/ERK signaling, promoting neuronal survival, growth, and repair, which is particularly important in neurodegenerative diseases such as AD and PD." (PMID 40926269, 2025). "For example, neurotrophic factors (BDNF, HGF, and VEGF) have been used to prime MSCs in neurodegenerative diseases." (PMID 38167146, 2024). "This can be considered to contribute to the downregulation of the BDNF/PI3K/Akt pathway, thereby impacting neurodegenerative diseases." (PMID 38397828, 2024). "This review explores the impact of physical exercise on brain-derived neurotrophic factor (BDNF) and its relationship with neurodegenerative diseases." (PMID 39935805, 2024). "Different reports put in evidence that BDNF and NT3 exhibit a significant therapeutic potential in the treatment of neurodegenerative diseases." (PMID 39334869, 2024). "Gothelf and collaborators demonstrated that the CM derived from neurotrophic factor-secreting MSCs was enriched with BDNF, VEGF-A, and HGF and has been used effectively to have protective effects in several animal models of neurodegenerative diseases." (PMID 35055049, 2022). "Over the past two decades, regulation of the activity of neurotrophinreceptors, and the brain-derived neurotrophic factor (BDNF) in particular, hasbeen viewed as a new strategy for treating neurodegenerative diseases." (PMID 36694902, 2022). "Brain derived neurotrophic factor (BDNF) represents one of the most promising and intensely studied targets in neurodegenerative disease as it has been shown to delay or even reverse disease progression in PD." (PMID 33953687, 2021). "Furthermore, the effects of AM on induction of signaling pathways involved in the growth, development, and repair of motor neurons, as well as increased BDNF expression suggest that AM may play beneficial roles in protecting motor neurons against neurodegenerative diseases that target SM neurons." (PMID 34712429, 2021). "Studies have shown that BDNF and GDNF have significant repair and protection effects on neurodegenerative diseases, including promoting axonal regeneration and reducing apoptosis." (PMID 33407864, 2021). "In particular, the brain-derived neurotrophic factor (BDNF) is essential for the survival and normal functioning of mature neurons and its level are markedly depressed in neurodegenerative diseases." (PMID 33801925, 2021). "Brain-derived neurotrophic factor (BDNF), a key regulator of neuronal survival, was suggested to play an important role in the pathophysiology of neurodegenerative diseases including AD, FTD, and DLB." (PMID 34046409, 2021). "More recently, fingolimod was shown to increase brain-derived neurotrophic factor (BDNF) mRNA and protein levels in mouse models of different neurological or neurodegenerative diseases in the cortex, hippocampus, and striatum." (PMID 33255764, 2020).
neurodegenerative disease (continued). "PS confers neuroprotective effects via elevation of brain gamma-aminobutyric acid (GABA) and brain-derived neurotrophic factor (BDNF) levels, and inhibition of the MAO activity, supporting a potential role for the treatment of neurodegenerative diseases." (PMID 32547358, 2020). "In agreement with previous studies reporting that CREB phosphorylation and BDNF expression are regulated by estrogen-receptor mediated manners, our data showed that increased levels of isoflavone aglycone may be involved in improving synaptic plasticity and defending neurodegenerative diseases." (PMID 31344808, 2019). "Brain-derived neurotrophic factor (BDNF), a neurotrophin essential for neuron survival and function, plays an important role in neuroprotection during neurodegenerative diseases." (PMID 28101532, 2017). "Several studies demonstrated that hippocampal BDNF and CREB are important in long-term memory formation, and play important roles in pathological conditions and neurodegenerative diseases such as AD." (PMID 25231482, 2014). "It suggests that RSV may help prevent or alleviate cognitive dysfunction in patients with various types of cancer undergoing chemotherapy due to BDNF/CREB/ERK 1/2 modulation and may have a potential benefit in neurodegenerative diseases." (PMID 40358798, 2025). "Moreover, recent studies demonstrate asiaticoside’s role in promoting neurogenesis via brain-derived neurotrophic factor (BDNF) upregulation, suggesting potential for neurodegenerative disease therapies." (PMID 40724583, 2025). "In the context of neurodegenerative diseases, CGA and NCGA exert neuroprotective effects via three mechanisms: alleviating oxidative stress, reducing neuronal inflammation, and enhancing the expression of brain-derived neurotrophic factor (BDNF)." (PMID 40431287, 2025). "For example, genetic alterations can enhance NSC functionality by promoting the release of neurotrophic factors such as brain-derived neurotrophic factor (BDNF) and glial cell line-derived neurotrophic factor (GDNF), which are vital for neuronal sustenance in neurodegenerative diseases." (PMID 40612293, 2025). "Our results showed an increased Tau phosphorylation, β-amyloid, and BDNF protein expression (although not significantly), suggesting that these CTs modulate neurotoxicity and potentially contribute to neurodegenerative diseases." (PMID 41424770, 2025). "In other words, exercise is an important non-pharmacological way to regulate BDNF expression in the brain, playing a positive role in promoting learning and memory and improving neurodegenerative diseases." (PMID 40606229, 2025). "Brain-derived neurotrophic factor (BDNF) plays a crucial role in neuroplasticity, neurogenesis, and neuronal protection, all of which are fundamental for maintaining optimal brain function and preventing neurodegenerative diseases." (PMID 39935805, 2024). "Furthermore, our data indicated increased PSD95, BDNF, and Syn protein expression and reduced tau protein phosphorylation following HBOT, suggesting a potential impact on neurodegenerative diseases." (PMID 38435399, 2024). "Among the hub genes, IL-10 hub genes may help to discover targeted therapies for neurodegenerative disease because IL10 reduces TNF-α production in PD and increases Brain-derived neurotrophic factor (BDNF) levels." (PMID 39432502, 2024). "When the levels of CaMkII and AMPK are reduced at the onset of neurodegenerative disease, the consequent reduced ability to express PGC-1α, FNDC5, BDNF, NGF, and GDNF could lead to cognitive dysfunction and deteriorating physical fitness." (PMID 35805580, 2022). "A comprehensive transcriptome analysis in Friedreich’s ataxia (FRDA) patients, a hereditary neurodegenerative disease characterized by guanine-adenine-adenine (GAA) nucleotide repeat expansion in the first intron of the frataxin (FXN) gene, identified BDNF and FXN as novel targets of miRNAs." (PMID 35743271, 2022).
neurodegenerative disease (continued). "Rather, it suggests that the pattern of BDNF/pro-BNDF, similar in ALS and AD patients, may be a typical feature of neurodegenerative diseases." (PMID 35625004, 2022). "Some NTFs such as BDNF, CNTF, and GDNF are promising candidates for future treatment as they affect the glial activation status and have a beneficial effect on the outcomes of neurodegenerative diseases." (PMID 33802760, 2021). "Moreover, we showed that hsa-miR-933 can regulate a target of ATF2, brain-derived neurotrophic factor (BDNF), to modulate the optimal expression of ATF2 in neuron cells to render neuroprotection for the inhibition of neurodegenerative diseases." (PMID 32993798, 2020). "For instance, using a medium-based approach (similar to pre-licensing), MSCs can be induced to secrete elevated levels of neurotropic factors, including GDNF, BDNF, VEGF, and HGF, which have been shown to have protective effects in animal models of neurodegenerative diseases." (PMID 33551729, 2020). "The modulation of REST/NRSF, its target gene SNAP-25 and BDNF expression by mGluR5 NAM may therefore represent a novel pharmacological tool to halt the progression of HD and potentially other neurodegenerative diseases." (PMID 32859226, 2020). "Plasma exosomal BDNF level has been assessed concerning healthy aging, but not in patients with neurodegenerative diseases." (PMID 32932791, 2020). "Although the Rheb–mTOR signaling pathway may act as a double-edged sword in neurodegeneration, it is a central regulator of NTFs such as BDNF, CNTF, and GDNF and thus is a potential therapeutic target for neurodegenerative diseases." (PMID 32188096, 2020). "On the other hand, nerve growth factor (NGF), brain-derived neurotrophic factor (BDNF), neurotrophins like NT-3, NT-4, NT-5, have attracted attention as potential therapeutics for severe neurodegenerative diseases such as AD or as regeneration-promoting compounds." (PMID 32545418, 2020). "Brain-derived neurotrophic factor (BDNF) is a potent biological agent that maintains cell viability and functional neuron activity in various pathological states, including severe genetically determined neurodegenerative diseases." (PMID 32733889, 2020). "Cumulative data from preclinical studies show the utility of BDNF and CNTF for conferring various neuroprotective effects led to the idea that these NTFs could be a clinically applicable therapeutic target in neurodegenerative diseases." (PMID 31766645, 2019). "Based on these, GPS may be effective in inhibiting the progress of neurodegenerative diseases by improving memory functions due to its anti-inflammatory activities and appropriate modulation of NF-κB/iNOS/TLR4/BDNF." (PMID 30018656, 2018). "Brain-derived neurotrophic factor (BDNF) is a neutrotrophic factor essential for the survival and differentiation of neurons and is considered a key target in the pathophysiology of various neurodegenerative diseases, as for example AD." (PMID 30428894, 2018). "Instead, together with the five upstream signalling factors (IGF1, BDNF, ZAP70, MYC, and cyclosporin A) they could help uncover the molecular mechanisms mediating AD or different neurodegenerative diseases." (PMID 26059363, 2015). "In conclusion, BDNF combined with NGF significantly improved NSC neuronal differentiation, which may provide support for the practical application of NSCs in neurodegenerative diseases." (PMID 25051506, 2014). "In conclusion, conditional BDNF delivery regulated by the GFAP promoter in astrocytes could well be a therapeutic strategy for treatment of HD and other neurodegenerative diseases." (PMID 21985529, 2011). "Overall, targeting BDNF/TrkB/CREB and PI3K/AKT signaling pathways or their upstream pathways may offer potential therapeutic strategies for the treatment of neuroinflammatory and neurodegenerative diseases." (PMID 39981856, 2025).